LINC00304 (long independently transcribed non-coding RNA 304)
Synonyms: C16orf81; NCRNA00304; FLJ36701
Gene: Long non-coding RNA gene on chromosome 16 (89,159,146 to 89,164,245, forward strand). Ensembl gene ENSG00000180422.
Diseases named in the same sentence as LINC00304 in open-access papers:
LINC00304 is named in the same sentence as 2 diseases in open-access papers, as found by Europe PMC text mining. Sharing a sentence is not in itself a finding about the gene and the disease.
LINC00304 shares sentences with these, for which no sentence is quoted: gastric cancer (1 paper); tumor (1).